TRPV1 (transient receptor potential cation channel subfamily V member 1)
Diseases named in the same sentence as TRPV1 in open-access papers (continued):
Sharing a sentence is not in itself a finding about the gene and the disease.
diabetes (continued). "Further experiments will be needed to determine whether Ca2+ influx or H2O2–dependent specific cysteine residue oxidation and reversible disulfide bond formation underlies the accelerated TRPV1 current decay observed in Akita DRG neurons at 9 months of diabetes." (PMID 30795543, 2019). "In order to determine whether this decrease of TRPV1-expressing fibres is due solely to the denervation associated with diabetes, the number of TRPV1-immunoreactive fibres was correlated with the number of fibres obtained with the neuronal markers neurofilaments or peripherin." (PMID 17521436, 2007). "This gap is pivotal given that TRPV1 activation rescues neuronal damage in diabetes; TRPV1-[Ca2+]i-AMPK crosstalk coordinates mitochondrial biogenesis/fission in other cell types; and mitochondrial fragmentation drives SC apoptosis in DPN." (PMID 41346340, 2025). "TRPV1 activation exerts protective effects in diabetes, including mitigating oxidative stress in DRG and preserving vascular function." (PMID 41346340, 2025). "While current studies have begun to uncover genetic and epigenetic mechanisms regulating TRPV1 in the context of diabetes, several limitations remain." (PMID 41463571, 2025). "Consistent with this, altered TRPV1 signaling in human endothelial and endocrine tissues was identified, linking TRPV1 dysregulation to impaired vasodilatory responses and metabolic stress in patients with diabetes." (PMID 41463571, 2025). "Dysbiosis of the gut flora not only directly affects bile acid metabolism but also significantly correlates with diabetes-associated neuropathy through interactions with the bile acid receptor TGR5 and the ion channel TRPV1." (PMID 39619328, 2024). "In this study, a satellite network identified the up-regulated TRPV1 gene in individuals with diabetes-related complications." (PMID 39337580, 2024). "Intrathecal injection of P2X7 shRNA alleviates nociceptive reactions in rats with diabetic neuropathic pain involving TRPV1 via PKCε/P38 MAPK/NF-κB signaling pathway." (PMID 36430617, 2022). "A recent study showed that blocking lipid-TRPV1 (transient receptor potential vanilloid 1) channel interactions with a peptide prevented diabetes-induced endothelial dysfunction in mice." (PMID 35600482, 2022). "Multiple studies have shown that TRPV1 activation can alleviate diabetes and cardiovascular diseases such as atherosclerosis and hypertension." (PMID 36045746, 2022). "This progression and development of the diabetes is modulated by capsaicin expressing sensory neurons by ablating TRPV1." (PMID 36234927, 2022). "TRPV1-expressing sensory nerves are also thought to participate in the low-grade chronic inflammation that characterizes diabetes and metabolic syndrome." (PMID 36551210, 2022). "BBR have partially inhibited activation of TRPV1 by inhibiting inflammation and blocking the PKC pathway, thereby protecting peripheral neurons from damage caused by diabetes." (PMID 35153744, 2021). "Recently, data from our research group have shown that endothelium-specific 12/15-lipooxygenase knockout mice were protected against diabetes-induced endothelial dysfunction, similarly to TRPV1 knockout mice." (PMID 34680034, 2021). "Another possible TRPV1 antagonist is 4-(3-chloro-2-pyridinyl)-N-[4-81,1-dimethylethyl)phenyl]-1-piperazine-carboxamide (BCTC), which has previously been used for the antagonization of TRPV1 in a study of diabetes and in another study on pain relief." (PMID 34680034, 2021). "In several types of experimental models of neuropathies, such as sciatic nerve injury (SNL), diabetes, and paclitaxel models, TRPV1 expression in the spinal dorsal horn is upregulated." (PMID 34445514, 2021). "Further, recent evidence from our research group has shown that the eicosanoid 12(S)-hydroxyeicosatetraenoic acid (12(S)-HETE) specifically interacts with the TRPV1 channel, leading to diabetes-induced vascular complications." (PMID 34680034, 2021).
diabetes (continued). "The study aimed to investigate the role of α‐lipoic acid (ALA) on the regulation of transient receptor potential vanilloid‐1 (TRPV1) in dorsal root ganglion (DRG) neurons of rats with diabetes." (PMID 32175676, 2020). "Taken together, these findings demonstrate that endothelial TRPV1 plays a protective role under several pathological conditions, such as inflammation, diabetes, and atherosclerosis, while its role in brain ischemic remains to be determined." (PMID 32471282, 2020). "Animal models of induced diabetes have demonstrated increased TRPV1 expression that correlates to hyperalgesia and decreased TRPV1 expression in hypoalgesia, reflecting earlier and later manifestations of diabetic neuropathy, respectively." (PMID 30795543, 2019). "We investigated the expression and functional activity of TRPV1 in DRG neurons of the Ins2+/Akita mouse at 9 months of diabetes using immunohistochemistry, live single cell calcium imaging, and whole-cell patch-clamp electrophysiology." (PMID 30795543, 2019). "Previously, we determined the role of capsaicin-sensitive, TRPV1-expressing nerves in experimental diabetes." (PMID 31344877, 2019). "We propose that in poorly controlled diabetes, the accelerated rate of capsaicin-sensitive TRPV1 current decay in DRG neurons decreases overall TRPV1 activity and contributes to peripheral neuropathy." (PMID 30795543, 2019). "This is consistent with our calcium imaging and electrophysiology data revealing that TRPV1 activity decays much faster in Ins2+/Akita DRG neurons at 9 months of diabetes." (PMID 30795543, 2019). "The gene expression of TRPV1 in bladder-innervating dorsal root ganglia neurons was observed in STZ-induced diabetes rat model at 4 weeks after STZ injection, and bladder detrusor strips contractions response to CAP markedly decreased." (PMID 30717724, 2019). "This review explores TRPV1 structure and modulation and will focus on its involvement in energy homeostasis, diabetes, and possible pharmacological manipulation." (PMID 30108548, 2018). "TRPA1 and TRPV1 are important molecules in the sensitisation of peripheral nociceptive afferents, and TRPV1 is directly sensitised by high-glucose conditions in sensory neurons and during diabetes in vivo." (PMID 29930087, 2018). "The influence of hyperglycemia on TRPV1 channels expressed in sensory neurons has been studied before in animal models of diabetes." (PMID 29474476, 2018). "The transient receptor potential vanilloid 1 (TRPV1) channel plays a central role in such sensory abnormalities and shows elevated expression levels in animal models of diabetes." (PMID 29474476, 2018). "More studies are needed to establish the role of TRPV1 and its signaling in the development and progression of kidney disease due to diabetes." (PMID 30583465, 2018). "Our previous studies suggest that activation of TRPV1 is a potential therapeutic target for obesity, hypertension, atherosclerosis and diabetes." (PMID 23607427, 2013). "In disease conditions such as diabetes, the expression and function of TRPV1 is altered in spinal dorsal horn." (PMID 19208258, 2009). "TRPV1 expressing neurons in pancreas are also shown to play a role in beta cell function and diabetes pathoetiology." (PMID 18312687, 2008). "Here, we have shown that TRPV1 is a major player, but questions still exist with respect to how TRPV1 function and expression are modulated in diabetes." (PMID 18312687, 2008). "In this study, we have used STZ-induced and transgene-mediated diabetes models to study the role of TRPV1 in DPN." (PMID 18312687, 2008). "In the present study, we have demonstrated that TRPV1 is decreased in both intra- and sub-epidermal fibres in diabetes resulting in the hypo-sensitivity typical of diabetic neuropathy." (PMID 17521436, 2007).
diabetes (continued). "These cytokines promote microglial activation and increase central TRPV1 expression and sensitization, thereby linking gut dysbiosis and systemic inflammation to neuroinflammatory responses and behavioral changes observed in diabetes." (PMID 41463571, 2025). "Although diabetes alters TRPV1 currents in DRG neurons, SC Ca2+ dynamics remain largely unexplored." (PMID 41346340, 2025). "Studies in diabetic rodent models, including streptozotocin-induced diabetic rats, obese Zucker rats, and high-fat diet-fed mice, have shown that TRPV1 ablation improves glucose tolerance, reduces obesity, and highlights its potential as a therapeutic target for diabetes and weight management." (PMID 40964166, 2025). "However, the majority of the DPN samples, particularly the DRGs obtained from donors who had established diagnoses of diabetic peripheral neuropathy or diabetes-related amputation, showed a drastic decrease in TrpV1 protein expression throughout the DRG." (PMID 40325011, 2025). "HUCMSCs ameliorate diabetic neuropathic pain primarily through activation of the TRPV1-[Ca2+]i-AMPK signaling pathway in SCs, which may provide a new molecular target for enhancing the clinical therapeutic effect of HUCMSCs on DPN." (PMID 41346340, 2025). "Given our concern regarding the role of TRPV1 in insulin secretion, as well as its potential involvement in diabetes-related vascular lesions and neuropathy, we posit that TRPV1 represents a promising avenue for future research into the pathogenesis and treatment of diabetes." (PMID 38255767, 2024). "In individuals with diabetes, the TRPV1 channel may contribute to the sensory disturbances of diabetic peripheral neuropathy, which in turn drives diabetic neuropathic pain." (PMID 38255767, 2024). "Interestingly, another study indicates that CAP can improve the endothelial dysfunction of diabetes by activating TRPV1/eNOS to reduce oxidative stress and increase NO in vascular endothelial cells of hyperglycemic mice." (PMID 38255767, 2024). "GLP‐1 secretion stimulated by TRPV1 activation could be a promising approach for diabetes intervention." (PMID 38628217, 2024). "The authors speculated that TRPV1 channels directly regulate MBF and impairment of TRPV1 channels could contribute to vascular dysfunction that is typically observed in diabetes." (PMID 33716794, 2021). "Moreover, TRPV1-mediated autophagy rescued mouse cardiac function in a mouse model of streptozotocin-induced diabetes mellitus." (PMID 35115924, 2021). "Our findings demonstrated that ALA may alleviate neuropathic pain in diabetes by regulating TRPV1 expression via affecting NF‐κB." (PMID 32175676, 2020). "Our findings demonstrated for the first time that ALA might alleviate neuropathic pain and reduce the excitability of DRG neurons in diabetes by suppressing TRPV1 expression via inhibiting NF‐κB activation." (PMID 32175676, 2020). "For example, patients with advanced diabetes may lose most of their TRPV1+ afferents as implied by a murine model of diabetic peripheral neuropathy." (PMID 33391007, 2020). "We propose that the accelerated decay rate of capsaicin-induced TRPV1 activity may contribute to reduced pain sensation in end-stage diabetes." (PMID 30795543, 2019). "Long-term in vivo treatment with antioxidants in diabetic Akita mice will be needed to provide evidence whether an association exists between long-term ROS accumulation and the accelerated kinetics of TRPV1 current decay observed in end-stage diabetes." (PMID 30795543, 2019). "TRPV1-mediated inflammation of pancreatic islet cells together with its facilitation of glucose-like peptide-1 secretion in the gut illustrates the new perspectives for use of TRPV1 modulators in diabetes therapy." (PMID 31263706, 2019). "It has been previously shown that the chemical induction of diabetes by STZ was increased TRPV1 expression, but whether channel expression is altered in diabetes, particularly in early stages of the disease, remains unclear." (PMID 29474476, 2018).
diabetes (continued). "Interestingly, Trpv1−/− mice exhibit increased sensitivity to insulin, raising the possibility of its involvement in diabetes." (PMID 27854251, 2016). "That is, diabetes-induced modulation of T-type channels may depend upon TRPV1 and ASIC sensory pathways in caps+ and caps−lpH+ neurons, respectively." (PMID 25986602, 2015). "The present study was designed to explore in a STZ-induced diabetes mellitus rat model whether the expression of TRPV1, a protein known to play an essential role in thermal hyperalgesia, is correlated with the development of mechanical allodynia." (PMID 25020137, 2014). "These diabetes-induced NGF modifications are associated with the activation of JNK and p38, with the repression of the transcription factor Nf-κB and with the upregulation of the ion channel TRPV1." (PMID 23710226, 2013). "Our previous study showed that TRPV1 activation-stimulated GLP-1 secretion could be a promising approach for the intervention of diabetes." (PMID 23607427, 2013). "The augmented response measured in neurons from diabetic animals following stimulation with capsaicin suggests that the function or expression of TRPV1 might be altered by diabetes." (PMID 23662103, 2013). "In this study, we used both STZ- and transgene- (TCR-SFE/Ins-HA;) mediated Type 1 diabetes (T1D) models to determine whether TRPV1 expression and function were altered with changes in thermal pain sensitivity in diabetes." (PMID 18312687, 2008). "Therefore, as diabetes progresses, modulation of TRPV1 has the potential to contribute to many complications such as CNS, cardiovascular, respiratory and urinary disturbances." (PMID 18312687, 2008). "The observed decrease of TRPV1 may have been due simply to an overall reduction of innervation, a common feature of diabetes." (PMID 17521436, 2007). "Sensitization of TRPV1 by phosphorylation could account for the hyperalgesic phenotype seen in this animal model of diabetes." (PMID 15857517, 2005). "The role of TRPV1 in animal models of diabetes has been suggested." (PMID 15857517, 2005). "Since insulin/IGF-I levels and PKC activity are altered in diabetes, we speculate that abnormalities in TRPV1 function may contribute to neuropathy in diabetes." (PMID 15857517, 2005). "In addition, some studies have shown that the inhibition of TRPV1 may improve diabetes-induced endothelial dysfunction and induce vascular regeneration in diabetic mice, and may improve insulin resistance." (PMID 38255767, 2024). "Since vascular TRPV1 receptors seem to be more resistant to metabolic changes of the peripheral tissue than neuronal TRPV1 receptors, hyperinsulinemia or diabetes mellitus may differentially affect the TRPV1 mediated dilatory and constrictor mechanisms further worsening tissue perfusion." (PMID 35033025, 2022). "Indeed, preliminary data from our laboratory clearly indicate that as a function of diabetes, guanfacine suppresses the increase in mRNA expression of TRPV1 and TRPA1 in several regions of the central nervous system including pons, LSSC, and DRG (unpublished data)." (PMID 36297581, 2022). "On the contrary, inhibition of the TRPV1 channel of the DRG could reduce diabetes-mediated pain." (PMID 36430617, 2022). "In addition, data suggest that CBS, TRPA1, TRPV1 and TRPC channels could be potential targets for the treatment of peripheral neuropathy associated with diabetes." (PMID 30602386, 2019). "Thus, it remains to be determined whether cross-desensitization or cross-activation between TRPA1 and TRPV1 would prevail in regulating TRPV1 current kinetics in diabetes." (PMID 30795543, 2019). "TRPV1 is a non-selective cation channel and has been linked to the development and progression of type 1 diabetes mellitus and T2D, and recent reviews have discussed its role in diabetes mellitus and obesity in further detail." (PMID 28421037, 2017). "Therefore, capsaicin/TRPV1 signaling can limit glucose levels increase and diabetes development." (PMID 27367653, 2016).
diabetes (continued). "As a result, patients with diabetes may have an impaired regulation of blood flow leading to the dominance of smooth muscle TRPV1 mediated vasoconstrictions over the physiological sensory neuronal TRPV1 mediated vasodilations." (PMID 24250792, 2013). "Participant characteristics of people with Type 2 Diabetes Mellitus (mean ± SD), in the total cohort and by TAS1R3 rs307355 and TRPV1 rs4790522 genotypes, in an additive, recessive and dominant manner." (PMID 40680045, 2025). "This suggests that in the early stage of diabetes, DRG neurons are affected by high glucose and enhance TRPV1-mediated current through PKC and Src kinase signal transduction." (PMID 38255767, 2024). "According to the findings, in the DRGs of mice and rats with diabetes mellitus, injections of antioxidants such as selenium, melatonin, and Noopept reduced the oxidant, TRPM2, TRPM7, and TRPV1 stimulator effects of STZ." (PMID 38976129, 2024). "TRPV1 and substance P are known to be regulated by NGF and have been related to diabetes-induced neuropathy Mediators of inflammation, particularly the proinflammatory cytokines IL-1β and TNF-α play critical roles in various neuropathic pain conditions." (PMID 32104520, 2020). "Although TRPV1 expressing neuron percentage was increased in Ins2+/Akita DRGs at 9 months of diabetes compared to control, capsaicin-induced Ca2+ influx was smaller in isolated Ins2+/Akita DRG neurons, indicating impaired TRPV1 function." (PMID 30795543, 2019). "TRPV1 is also phosphorylated and sensitised through a PKC-dependent mechanism during diabetes in vivo." (PMID 29930087, 2018). "Neonatal ablation of TRPV1-expressing sensory neurons in non-obese diabetic (NOD) mice conferred long-term protection from diabetes, implicating a sensory-immune communication pathway in autoimmune β-cell destruction." (PMID 41463571, 2025). "For example, elimination of TRPV1+ sensory neurons (by using capsaicin, an active component of chili peppers) prevents insulitis and diabetes in diabetes-prone non-obese diabetic (NOD) mice." (PMID 37767094, 2023). "Capsaicin-induced permanent elimination of TRPV1-expressing pancreatic sensory neurons reduces islet infiltration, insulin resistance, and β-cell stress in neonatal diabetes-prone non-obese diabetic (NOD) mice." (PMID 27367653, 2016). "EA could revert neuropathic symptoms in the early diabetes, and its action is possibly exerted on mediators of DRGs neuron sensitization, such as NGF, MAPKs, and the TRPV1." (PMID 23710226, 2013). "The expression of TRPV1 has been shown to be decreased in the hearts of STZ-diabetic mice although Strecker and colleagues reported unaltered capsaicin-induced CGRP release from human right atrium from subjects with diabetes." (PMID 23662103, 2013). "Together these data demonstrate that STZ-induced diabetes does not alter thermal pain sensitivity in TRPV1 knock-out mice further suggesting TRPV1 plays a major role in diabetes-induced altered thermal pain sensitivity." (PMID 18312687, 2008). "For instance, in the absence of diabetes, endothelial TRPV1 activation may promote nitric oxide production and contribute to vasodilation." (PMID 35600482, 2022). "Increased TRPV1 expression in the superficial laminae I–II of the spinal dorsal horn has been reported in various types of pain, such as complete Freund’s adjuvant (CFA)-induced inflammatory pain, sciatic nerve injury, diabetes, and paclitaxel-induced neuropathic pain." (PMID 34445514, 2021). "In our study, TRPV1 protein expression was not up-regulated during diabetes development." (PMID 30602386, 2019). "The exact mechanism of sensitization of TRPV1 is not clear, but could be due to over compensation by other tropic factors, such as NGF in response to insulin deficiency or elevated PKC activity in diabetes." (PMID 15857517, 2005). "We found that experimental diabetes increased TRPC6, but not TRPV1 nor TRPA1, protein expression in DRG." (PMID 30602386, 2019).